IL18 (interleukin 18)
Diseases named in the same sentence as IL18 in open-access papers (continued):
Sharing a sentence is not in itself a finding about the gene and the disease.
prostate carcinoma (30 papers, 2011 to 2026). A carcinoma that arises from epithelial cells of the prostate gland. "Based on the results of this study, polymorphisms in CXCL10 A-1447G, IL-18 G-137C, and IL-18 C607A alleles were associated with an increased risk of prostate cancer." (PMID 39359425, 2024). "According to the results, the mutant alleles in polymorphisms CXCL10 A-1447G, IL-18 G-137C, and IL-18 C-607A alleles were associated with an increased chance of prostate cancer in this population." (PMID 39359425, 2024). "The presence of one mutant allele in the IL-18 G-137C polymorphism significantly increased the chance of prostate cancer by 5.583 times, and the presence of two mutant alleles significantly increased the chance of prostate cancer by 9.571 times." (PMID 39359425, 2024). "The presence of one mutant allele in the IL-18 C607A polymorphism significantly increased the chance of prostate cancer by 5.359 times, and the presence of two mutant alleles significantly increased the chance of prostate cancer by 7.083 times." (PMID 39359425, 2024). "Previous studies have suggested that IL-18 expression in prostate cancers was associated with a favorable outcome." (PMID 37528490, 2023). "For example, a drug which targets and activates NLRP3 can suppress IL-1β and IL-18 while causing prostate cancer pyroptosis and then limiting the scale and scope of inflammation." (PMID 34869390, 2021). "Second, a systematic review of the association of IL-18 -607 C/A polymorphism and prostate cancer risk is statistically far more powerful than any single study." (PMID 31244277, 2019). "AA: OR=0.37, 95%CI=0.28-0.48, P=0.000) models, for Caucasians, IL-18 -607 C/A polymorphism was significantly associated with prostate cancer risk in allele contrast (C versus." (PMID 31244277, 2019). "In general, IL-18 -607 C/A polymorphism plays different roles in prostate cancer susceptibility among different ethnic subgroups." (PMID 31244277, 2019). "In the sub-group analysis according to ethnicity, for Asians, IL-18 -607 C/A polymorphism was significantly associated with prostate cancer in allele contrast (C versus." (PMID 31244277, 2019). "Larger scale primary studies with the consideration of gene-gene and gene-environment interactions are required to further evaluate the interaction of IL-18 -607 C/A polymorphism with prostate cancer susceptibility." (PMID 31244277, 2019). "The currently available data on the association between IL-18 -607 C/A polymorphism and prostate cancer in Caucasians are still very limited, so it should be interpreted with caution." (PMID 31244277, 2019). "In the sub-group analysis according to ethnicity, showed in the meta-analysis, for Asians, IL-18 -607 C/A polymorphism was significantly associated with prostate cancer in allele contrast (C versus." (PMID 31244277, 2019). "This research is trying to determine that IL-18 -607 C/A polymorphism confers susceptibility to prostate cancer." (PMID 31244277, 2019). "For Caucasians, IL-18 -607 C/A polymorphism was significantly associated with prostate cancer risk in allele contrast (C versus." (PMID 31244277, 2019). "First, this is the first meta-analysis on the association between IL-18 -607 C/A polymorphism and prostate cancer risk." (PMID 31244277, 2019). "This meta-analysis has shown that IL-18 -607 C/A polymorphism contributes to a decreased risk of prostate cancer risk in the Asian population but an increased risk in the Caucasian population." (PMID 31244277, 2019). "IL-18 is produced in prostate cancer cells after IFNα treatment, and high IL-18 expression is associated with beneficial clinical effects." (PMID 30158439, 2018). "Another indication for an important role of IL-18 in prostate cancer is that some genetic variants of the IL-18 promoter are associated with elevated prostate cancer risk in different populations." (PMID 30158439, 2018).
prostate carcinoma (continued). "While the role of IL-6 in prostate cancer is well documented, studies on serum IL-18 for its diagnostic utility in cancer are limited." (PMID 27429614, 2016). "A Mendelian randomization study, using GWAS summary data on 35 interleukins from large-scale proteomic studies across eight independent populations of European descent and data on 23 common cancers from the FinnGen Consortium, identified IL-18 as a risk factor for prostate cancer." (PMID 40718836, 2025). "Importantly, IL-18, one of the cytokines released upon pyroptosis, is a pro-inflammatory cytokine that has been implicated in prostate cancer." (PMID 37528490, 2023). "Variations in the DNA sequence of IL-18 gene promoter may influence the production and/or activity of IL-18, which modulates an individual’s susceptibility of prostate cancer." (PMID 31244277, 2019). "In the overall population, there is a significant association between IL-18 -607 C/A polymorphism and prostate cancer risk in recessive (CC versus CA/AA: OR = 0.20, 95% CI = 0.15-0.27, P = 0.000) or dominant (CC/CA versus AA:OR = 0.42, 95% CI = 0.30–0.57, P = 0.000) models." (PMID 31244277, 2019). "We found that, in the overall population, there is a significant association between IL-18 -607 C/A polymorphism and prostate cancer risk using a recessive (CC versus CA/AA: OR = 0.20, 95% CI = 0.15-0.27, P = 0.000) or dominant (CC/CA versus AA:OR = 0.42, 95% CI = 0.30–0.57, P = 0.000) model." (PMID 31244277, 2019). "Therefore, more studies of the Caucasian population are needed in the future to obtain more precise conclusions about the associations between IL-18 -607 C/A polymorphism and prostate cancer risk." (PMID 31244277, 2019). "In addition, the relationship between IL-18 -607 C/A (rs1946518) polymorphism and prostate cancer has been investigated in previous studies." (PMID 31244277, 2019). "Therefore, a meta-analysis of all eligible case-control studies was performed in order to verify the association between IL-18 -607 C/A polymorphism and prostate cancer risk in this article." (PMID 31244277, 2019). "Moreover, human prostate cancer cell lines and clinical PCa specimens are reported to express IL-18 receptor α and IL-18 expression was associated with better patient outcome." (PMID 21935389, 2011). "The current study was conducted to study the relationship between G-137C, C-607A, and A-1447G polymorphisms in the promoter of IL-18 and CXCL10 inflammatory genes with prostate cancer." (PMID 39359425, 2024). "On the other hand, in the tissue with prostate cancer, a positive IL-18 inflammation was found in the cytoplasm of neoplastic cells covering the prostate glandular epithelium and in the stromal cells of the prostate." (PMID 37847180, 2023). "A previous study found that NLRP12 inflammasome induces inflammatory events during the development and progression of aggressive prostate cancer via regulating IL-1β and IL-18." (PMID 37658975, 2023). "The role of interleukin 18 and its pro-inflammatory properties are also analysed in relation to prostate cancer and its various stages of advancement, including its metastatic potential." (PMID 37847180, 2023). "The studies show that the concentration of IL-18 in the blood serum of patients with prostate cancer is significantly higher than in healthy patients from the control group (345 ± 94.8 pg/ml vs. 180 ± 54.1 pg/ml, p < 0.05)." (PMID 37847180, 2023). "In this in vitro setting, we detected significant reduction in TC2R prostate cancer cell viability when IL-27 was used alone or co-administered with IL-18 relative to untreated control (*, p < 0.05) and each single cytokine alone (#, p < 0.05)." (PMID 34209203, 2021). "In this manuscript, we describe the therapeutic administration of IL-27 in a sequential manner with IL-18 for treating prostate cancer." (PMID 34209203, 2021).
prostate carcinoma (continued). "NLRP12 has similar functions to TGF-β and can also promote the occurrence and development of prostate cancer by regulating caspase-1 and its downstream IL-1β and IL-18." (PMID 34869390, 2021). "We describe our findings on the effects of IL-27 gene delivery on prostate cancer cells and how sequential therapy with IL-18 enhanced the efficacy of IL-27." (PMID 34209203, 2021). "IL-18 expression in prostate cancer is also related to the pathologic stage and the transition from androgen-responsive to hormone-refractory of prostate cancer." (PMID 31244277, 2019). "In line with this and in contrast to IL-1β, overexpression of IL-18 in prostate cancer cells inhibits tumor growth in vivo." (PMID 30158439, 2018). "The intracellular inflammasomes NLRP3, NLRP12 and AIM2 can be triggered by several stimuli, and are responsible for IL-1 and IL-18 expression in prostate cancer." (PMID 30158439, 2018). "The inflammasome complex proteins ASC (apoptosis-associated speck-like protein containing a CARD) and pro-caspase-1, as well as its downstream targets IL-1β and IL-18 were confined to aggressive prostate cancer cells." (PMID 28663562, 2017). "The downstream targets, IL-1β and IL-18 pro-forms were primarily confined to aggressive prostate cancer cell lines PC3 and DU145." (PMID 28663562, 2017). "Study on a cohort of 149 patients demonstrated that serum IL-18 level was significantly higher in locally advanced prostate cancer as compared to healthy control and BPH." (PMID 27429614, 2016). "Here we investigated the potential of IL-18 as a cancer agent for PCa by using a murine orthotopic model of prostate carcinoma, the RM1 cell line." (PMID 21935389, 2011). "We have demonstrated in an immunocompetent orthotopic model of prostate cancer that intratumoral IL-18 has the ability to inhibit tumor growth." (PMID 21935389, 2011). "In this study, the potential of IL-18 as an immunotherapy for prostate cancer (PCa) was examined using the murine model of prostate carcinoma, RM1 and a bone metastatic variant RM1(BM)/B4H7-luc." (PMID 21935389, 2011). "This discrepancy suggests that post-transcriptional regulation may play a role in modulating IL-18 expression in prostate cancer." (PMID 37528490, 2023). "The present study aimed to determine the alterations in the serum levels of tumor markers used to evaluate cardiac, renal and liver function, and detect the interleukin (IL)-18 rs1946518 polymorphism in breast (BC), colorectal (CRC) and prostate cancer (PCa) patients." (PMID 33507690, 2021). "Recent studies also reported that an increased NLRP12 expression is associated with the progression of prostate cancer in the absence of increased levels of mature IL-1β or IL-18 by cancer cells." (PMID 34203890, 2021). "After screening the titles and abstracts, 21 studies were excluded because they were not relevant to the relationship between IL-18 polymorphism and the risk of prostate cancer." (PMID 31244277, 2019). "Since inflammasome assembly is considered a master regulator of inflammation, determining the molecular function of NLRP12 as an upstream regulator of NF-κB, IL-1β, and IL-18 signaling will add to our understanding the molecular basis of inflammation induced prostate cancer." (PMID 28663562, 2017). "The dominant expression of inflammasome complex proteins (ASC and pro-caspase-1) in aggressive prostate cancer cell lines implicate the role of NLRP12 inflammasome provoking inflammatory events via regulating IL-1β and IL-18 in the development and progression of prostate cancer." (PMID 28663562, 2017). "Furthermore, a recent study demonstrated that an increased NLRP12 expression is associated with the progression of prostate cancer in the absence of increased levels of mature IL-1β or IL-18 by cancer cells." (PMID 36980199, 2023). "In addition, IL-18 is an critical genetic factor in the proliferation of prostate cancer." (PMID 31244277, 2019).
prostate carcinoma (continued). "Importantly, IL-18 has also been implicated in activating ILC2 responses in chronic myeloid leukemia and prostate cancer promoting immune suppression and tumor progression, raising the possibility that similar mechanisms may be involved also in thymic carcinoma." (PMID 41368637, 2025). "AIM2, an interferon (IFN) inducible protein, is constitutively down-regulated in prostate cancer, however, IFN-induced AIM2 inflammasome activation leads to increased production of IL-1β and IL-18 in prostate cancer cell lines." (PMID 30631327, 2018). "IFNs treated prostate cancer cell lines showed increased AIM2 activating inflammasome complex leading to production of IL-1β and IL-18." (PMID 27429614, 2016). "It is likely that additional factors are required to activate and organize the formulation of NLRP12 inflammasome complex, similar to activation of AIM2 by the interferons (IFNs) in prostate cancer cell lines activating AIM2 inflammasome leading to interleukins IL-1β and IL-18 production." (PMID 28663562, 2017). "Since IL-18 and IL-1β are produced in large quantities during NLRP3 inflammasome activation, current findings indicate that the NLRP3 inflammasome and its downstream pathways may promote prostate cancer progression." (PMID 40718836, 2025). "While IL-18 pro-form is low to non-detectable in LNCaP, LN3, 22Rv1, and VCaP, a longer incubation also revealed a very low expression of IL-1β pro-form in prostate cancer cell lines." (PMID 28663562, 2017).
renal fibrosis (30 papers, 2013 to 2025). A final common manifestation of a wide variety of chronic kidney diseases characterized by glomerulosclerosis and tubulointerstitial fibrosis. "This suggested that IL-18 deficiency attenuated renal fibrosis." (PMID 36379914, 2022). "Furthermore, renal tubular cells from DOCA-salt treated mice demonstrate increased expression of IL-18, while IL-18 deficient mice were protected from increased blood pressure and renal fibrosis." (PMID 36620210, 2022). "Further, IL-1R and IL-18 have been directly associated with the promotion of renal fibrosis." (PMID 31540220, 2019). "IL-18 deficiency protects against renal fibrosis by aldosterone-salt treatment." (PMID 29514661, 2018). "In contrast, the inhibition of IL-18 can reduce the advancement of renal fibrosis following IRI, further underscoring the important role of IL-18 in AKI and its complications." (PMID 40521043, 2025). "The consequently release of IL-1β and IL-18 activates macrophages in renal interstitium and aggravates tubular injury and renal fibrosis." (PMID 36732854, 2023). "More recently, inhibition of IL-18 by peritoneal doses of IL-18 Bp has been shown to reduce renal fibrosis following IRI." (PMID 36846323, 2023). "Promoting SIRT1 expression can inhibit pyroptosis of renal tubular epithelial cells, reduce the release of IL-18 and IL-1β, and alleviate the progression of renal fibrosis in children with CHn." (PMID 37534327, 2023). "The activation of the NLRP3 inflammasome promotes the activation of inflammatory caspases (caspase-1)-dependent pro-inflammatory hormones IL-1β and IL-18, which, in turn, promotes renal fibrosis." (PMID 36421424, 2022). "On the other hand, it was observed that in renal fibrosis, proximal tubular cells stimulated by IL-18 can induce the α-SMA, collagen I, and fibronectin production in a dose- and time-dependent manner." (PMID 36362582, 2022). "In IL-18 knockout mice given folate, compared to wild-type mice, tubular damage and necroptosis, transdifferentiation, and renal fibrosis were attenuated." (PMID 36379914, 2022). "IL-18 deletion reduced both M1 and M2 macrophages in kidneys preventing fibrosis starting renal fibrosis occurrence." (PMID 36379914, 2022). "The typical NLRP3/ASC/caspase-1/IL-1β/IL-18 axis promotes the pathophysiology of various kidney diseases by mediating inflammation, and this is likely a critical priming mechanism for renal fibrosis." (PMID 32039201, 2019). "Taken together, these findings suggested an important role for canonical NLRP3 inflammasome activation (the NLRP3 inflammasome-caspase 1-IL-1β/IL-18 axis) in renal fibrosis in the murine UUO model of CKD." (PMID 28348462, 2017). "This renal injury and fibrosis can be blocked with MRA treatment and is reduced in mice lacking galectin-3, PAI-1, interleukin-18 (IL-18), or inflammasome activation in macrophages, suggesting their involvement in the MR-mediated renal fibrosis." (PMID 28611666, 2017). "Together, it can thus be proposed that development of progressive renal fibrosis is primarily mediated via IL-18, while the role of upstream Nlrp3 is only minor." (PMID 24454932, 2014). "Inhibition of IL-18 has been demonstrated to attenuate the progression of renal fibrosis post-IRI." (PMID 40521043, 2025). "Previous studies showed that blocking IL-18 and IL-33 ameliorated renal fibrosis." (PMID 40131554, 2025). "IL-18 plays a pivotal role in the development of renal fibrosis following IRI, primarily by modulating inflammatory cell infiltration as well as cytokine and chemokine production and by promoting the transformation of bone marrow-derived M2 macrophages into myofibroblasts." (PMID 40521043, 2025). "Regarding the mechanisms of apoptosis and fibrosis, the natural IL-18 inhibitor IL-18BP has demonstrated dual protective effects in ischemia models, as it can decrease renal tubular cell apoptosis and delay the progression of renal fibrosis." (PMID 40521043, 2025).